NCOA3 (nuclear receptor coactivator 3)
Description:
Nuclear receptor coactivator that directly binds nuclear receptors and stimulates the transcriptional activities in a hormone-dependent fashion. Plays a central role in creating a multisubunit coactivator complex, which probably acts via remodeling of chromatin. Involved in the coactivation of different nuclear receptors, such as for steroids (GR and ER), retinoids (RARs and RXRs), thyroid hormone (TRs), vitamin D3 (VDR) and prostanoids (PPARs). Displays histone acetyltransferase activity. Also involved in the coactivation of the NF-kappa-B pathway via its interaction with the NFKB1 subunit.
Synonyms: AIB-1; pCIP; bHLHe42; SRC-3; TRAM-1; AIB1; RAC3; ACTR; p/CIP; CAGH16; TNRC16; KAT13B; SRC3; CTG26; TNRC14
Tractability: Small molecule: a structure with a bound ligand is known; it belongs to a druggable protein family. PROTAC: ubiquitination databases record sites on it; its protein half-life has been measured; a small molecule that binds it is known.
Target class: SRC family; Epigenetic regulator; Histone acetyltransferase; Writer
Gene: Protein-coding gene on chromosome 20 (47,501,864 to 47,656,877, forward strand). Ensembl gene ENSG00000124151.
Subcellular location: Cytoplasm; Nucleus
Subcellular location (Human Protein Atlas): Nucleoplasm; Cytosol
Pathways (Reactome):
Developmental Biology: Activation of anterior HOX genes in hindbrain development during early embryogenesis; Transcriptional regulation of white adipocyte differentiation
Signal Transduction: Estrogen-dependent gene expression; MAPK6/MAPK4 signaling
Gene expression (Transcription): MLL4 and MLL3 complexes regulate expression of PPARG target genes in adipogenesis and hepatic steatosis
Metabolism: PPARA activates gene expression
Gene Ontology:
Molecular function: disordered domain specific binding; histone acetyltransferase activity; nuclear receptor binding; protein binding; transcription coactivator activity; nuclear thyroid hormone receptor binding; RNA polymerase II complex binding; protein dimerization activity; protein-lysine-acetyltransferase activity; transcription coregulator activity
Biological process: cellular response to estradiol stimulus; positive regulation of keratinocyte differentiation; positive regulation of transcription by RNA polymerase II; retinoic acid receptor signaling pathway; vitamin D receptor signaling pathway; cell dedifferentiation; cellular response to hormone stimulus; positive regulation of stem cell population maintenance; regulation of stem cell division; chromatin remodeling; regulation of DNA-templated transcription
Cellular component: chromatin; cytoplasm; cytosol; extracellular exosome; nucleoplasm; nucleus; protein-containing complex
Genetic constraint (gnomAD): Loss-of-function variants: 43 observed, 147.53 expected, observed/expected ratio (o/e) 0.29, 90% interval 0.23 to 0.38. The upper end of that interval is the gene's LOEUF score, 0.38, which puts it in group 1 of 6, group 1 being the genes least tolerant of losing a copy. Missense variants: 1,441 observed, 1,748.1 expected, observed/expected ratio (o/e) 0.82, 90% interval 0.79 to 0.86. Synonymous variants: 509 observed, 591.45 expected, observed/expected ratio (o/e) 0.86, 90% interval 0.8 to 0.93.
Homologues: Orthologues: chimpanzee NCOA3 (99% identical), macaque NCOA3 (98% identical), dog NCOA3 (92% identical), guinea pig NCOA3 (87% identical), pig NCOA3 (86% identical), rabbit NCOA3 (85% identical), rat Ncoa3 (83% identical), mouse Ncoa3 (83% identical), tropical clawed frog ncoa3 (71% identical), zebrafish ncoa3 (51% identical), Drosophila melanogaster tai (22% identical). Paralogues in human: NCOA2 (42% identical), NCOA1 (32% identical).
Diseases named in the same sentence as NCOA3 in open-access papers:
NCOA3 is named in the same sentence as 133 diseases in open-access papers, as found by Europe PMC text mining. Sharing a sentence is not in itself a finding about the gene and the disease. The quoted sentences say what the papers report.
breast carcinoma (243 papers, 2002 to 2026). "One previous study implicated that miR-17 and miR-20b attenuated breast cancer resistance to Taxol by targeting nuclear receptor coactivator 3 (NCOA3)." (PMID 35760798, 2022). "Metabolic enzyme PFKFB4 promotes transcriptional co-activator SRC3 (nuclear receptor coactivator 3) for breast cancer carcinogenesis and is associated with poor prognosis of breast cancer." (PMID 34408553, 2021). "Loss of miR-17 and miR-20b confers Taxol resistance in breast cancer by enhancing expression of nuclear receptor coactivator 3 (NCOA3), which is significantly upregulated in Taxol-resistant breast cancer cells." (PMID 33182737, 2020). "NCOA3 encodes nuclear receptor coactivator 3, a member of the nuclear receptor co-activator family known to be overexpressed in breast cancer and essentially involved in estrogen-mediated cancer cell proliferation." (PMID 32212785, 2020). "NCOA3, also known as steroid receptor coactivator-3 (src-3), was described as being associated with uterine endometrial cancer or other cancers, e.g., breast cancer." (PMID 29747396, 2018). "Together, our results indicated that loss of miR-17 and miR-20b enhanced breast cancer resistance to taxol by upregulating NCOA3 levels." (PMID 27831559, 2016). "A polymorphism in NCOA3 has been associated with breast cancer, and its amplification has been associated with survival in ER-positive tumors." (PMID 25950620, 2015). "In breast cancer, NCOA3 is overexpressed and its overexpression is associated with HER2 activation, endocrine therapy resistance and poor disease-free survival (DFS)." (PMID 26287601, 2015). "Since overexpression of NCOA3 in breast cancer has been shown to be associated with clinical parameters, we were interested if high PLAC1 expression is associated with NCOA3 overexpression." (PMID 24304549, 2013). "The genetic variants within ER cofactors have not been systematically investigated in term of association with breast cancer risk, although some coding variants within individual genes, such as NCOA3 and CCND1, have been investigated." (PMID 21269472, 2011). "It was found overexpressed in 60 % breast cancer patients, leading to tamoxifen resistance and worse clinical outcome, while the NCOA3 deficiency could suppress the tumor initiation and progression in mice model with breast cancer." (PMID 34593007, 2021). "In addition, increased expression of NCOA3, with implications for AR activation, and variation in the length of the polyQ repeat in the NCOA3 gene have been associated with bone cancer, epithelial ovarian cancer, colorectal cancer, and breast cancer in humans." (PMID 32854182, 2020). "Xiang Ao and his colleagues examined 55 pairs of breast cancer tissues and adjacent normal tissues in total, and found that resistance to taxol in breast cancer patients increased with the loss of miRNA-17 and miRNA-20b, by the up-regulation of nuclear receptor co-activator 3 (NCOA3) levels." (PMID 31615089, 2019). "The top hub gene NCOA3 plays an essential role in the network, and the dysregulation of it can disturb the balance of the network and may further cause breast cancer." (PMID 28482794, 2017). "The 2 BRCA-related miRNA sponge interactions can also form BRCA-related miRSCoPPI sub-network, and the dysregulation of the top hub gene NCOA3 may cause breast cancer." (PMID 28482794, 2017). "Moreover, our results showed that high expression of NCOA3 identified in taxol-resistant breast cancer cells was associated with loss of miR-17 and miR-20b." (PMID 27831559, 2016). "Accordingly, overexpression of NCOA3 causes spontaneous development of mammary tumors." (PMID 26287601, 2015). "Since depletion of NCOA3-p300-NF-κB members in breast cancer cells caused the downregulation of antiapoptotic genes, we next investigated whether depletion of NCOA3-p300-NF-κB members would have an anti-proliferative/anti-survival effect on breast cancer cells." (PMID 36853387, 2023).
breast carcinoma (continued). "In human breast cancer, NCOA3 is amplified and overexpressed at transcript and protein level in a significant portion of tumors and its particular relevance is underlined from the induction of spontaneous mammary tumors in mice overexpressing NCOA3 in mammary epithelial cells." (PMID 24304549, 2013). "NCOA1 and NCOA3 are overexpressed in human breast cancer, and their inhibition or deletion has attenuated cancer progression in various models of multiple types of cancer." (PMID 40023399, 2025). "They found that these compounds had a longer half-life, reduced NCOA3 levels, decreased proliferation and migration in breast cancer cells, and attenuated tumor growth in mice." (PMID 40023399, 2025). "In BrCa, amplification of the coactivator NCOA3/AIB1 (amplified in breast cancer 1) enhances estrogen receptor (ER) α activity and contributes to resistance toward selective estrogen receptor modulators such as tamoxifen." (PMID 41150850, 2025). "Using small molecule inhibitors to target NR5A2 or NCOA3 can significantly enhance the anti-cancer effects of BET inhibitors in breast cancer in vitro and in vivo." (PMID 39664391, 2024). "For example, overexpression or amplification of the steroid receptor coactivator-3 (SRC-3/NCOA-3/AIB1) has been associated with enhancement of ERα ligand-independent transactivation and poor prognosis in ERα positive breast cancer." (PMID 38122900, 2024). "Comparing our findings of an ER interactome with those previously reported in ER+ breast cancer cells, only three ER interactors were common to all studies (NCOA3, NCOR2, and TRIM33)." (PMID 38473207, 2024). "The results presented here have led us to propose a schematic model that explains how NCOA3 coordinates with p300 and NF-κB to transactivate antiapoptotic genes in breast cancer cells." (PMID 36853387, 2023). "NCOA3 overexpression has been observed in breast cancer cells, and mice that overexpress NCOA3 show increased cell proliferation and can generate breast tumors." (PMID 36853387, 2023). "Previously, NCOA3 was reported to play a critical role in human diseases such as breast cancer, osteoarthritis, hepatic injury, and fibrosis." (PMID 36658474, 2023). "NCOA3 is amplified in 5% to 10% of human breast cancers and mRNA is found overexpressed in approximately 30% to 60% of breast cancer cases." (PMID 37711895, 2023). "Three nuclear receptor coactivators (NCOAs), namely NCOA1, NCOA2, and NCOA3, which are frequently overexpressed in breast cancer cells and are involved in estrogen-mediated cancer cell proliferation." (PMID 36853387, 2023). "NCOA3 was initially found to be highly expressed in breast cancer, and it was later discovered to be amplified in many other malignant diseases." (PMID 35252174, 2022). "After silencing circ_0001667, the malignant progression and chemotherapeutic resistance of DOX-resistant breast cancer were inhibited by the miR-4458/NCOA3 (Nuclear receptor coactivator 3) axis." (PMID 37304411, 2022). "NCOA3 is amplified and expressed in a wide spectrum of human malignancy diseases, and studies have demonstrated that NCOA3 promoted EMT via the PI3K/AKT signalling in gastric cancer or through SNAI1 activation in breast cancer." (PMID 33289330, 2021). "Steroid receptor coactivator 3 (SRC-3/NCoA3/AIB1), is a key regulator of gene transcription and it plays a central role in breast cancer (BC) tumorigenesis, making it a potential therapeutic target." (PMID 33767353, 2021). "The expression of miR-17 and miR-20b was significantly suppressed in taxol-resistant breast cancer tissues and cells by upregulating nuclear receptor co-activator 3 (NCOA3)." (PMID 33435254, 2021). "Other well-known breast cancer associated genes that were highly expressed in both cell systems included GATA3, GNAS, FASN and NCOA3." (PMID 34680485, 2021). "NCOA3 also drives the formation of cancer stem-like cells and supports tumor outgrowth in breast cancer models." (PMID 32212785, 2020).
breast carcinoma (continued). "On the other hand, increased levels of NCOA3 have been shown to favor the functional interaction of ERα and promote the estrogen-dependent mitogenic stimulation of breast cancer cells." (PMID 30941313, 2019). "Nuclear steroid receptor coactivator-3 (SRC-3/AIB1/NCOA3) was originally identified as a gene amplified in nearly 10% of breast cancers but has been shown to be overexpressed in 50–60% of cases with weak to absent expression in normal mammary tissue." (PMID 31635050, 2019). "NCOA3 has been found to be elevated in breast cancer, liver cancer, prostate cancer, and colorectal cancer, correlated with poor prognosis in most cases, and a vital regulator in the process of tumorigenesis, progression, metastasis, and survival." (PMID 29360267, 2018). "NCOA3 was found to be overexpressed in >60% of primary breast tumours; however its gene is amplified in only 5%–10% of breast cancers." (PMID 29545931, 2018). "NCOA3 not only functions to promote breast cancer development, it also participates in resistance to anti-hormonal therapy." (PMID 29545931, 2018). "Previous study indicate that high expression of NCOA3 can suppress cells apoptosis induced by histone deacetylase inhibitor in breast cancer." (PMID 29653596, 2018). "Analysis of copy number alteration (CNA) of NCOA3 in the BRCA-The Cancer Genome Atlas (TCGA) data sets, which is one of the largest data sets containing matched DNA copy number alteration of primary breast cancers revealed amplification of NCOA3 gene." (PMID 29545931, 2018). "Increased expression of NCOA3 is strongly correlated with shorter disease-free and overall survival in breast cancer." (PMID 29545931, 2018). "We show that NCOA3 regulates the expression of PERK and expression levels of NCOA3 mRNA correlates with the transcript levels of PERK in breast cancer cohort of TCGA." (PMID 29545931, 2018). "In conclusion, we had identified downregulation of miR-17 and miR-20b induced taxol resistance in breast cancer by upregulating NCOA3." (PMID 27831559, 2016). "Consistent with the results from breast cancer tissues, higher protein and mRNA levels of NCOA3 were found in taxol-resistant breast cancer cells compared with the taxol-sensitive parental cells." (PMID 27831559, 2016). "Our results showed taxol-resistant breast cancer tissue specimens exhibited generally higher NCOA3 mRNA levels compared with taxol-sensitive tissues." (PMID 27831559, 2016). "In this study, nuclear receptor coactivator 3 (NCOA3) was found to be significantly increased in taxol-resistant breast cancer tissues and cells." (PMID 27831559, 2016). "In this study, NCOA3 mRNA levels were found to be significantly increased in taxol-resistant breast cancer." (PMID 27831559, 2016). "Here, we showed for the first time that NCOA3 is upregulated in breast cancer tissues derived from taxol-resistant patients, compared with the tumor samples from taxol-sensitive patients." (PMID 27831559, 2016). "These translational studies suggest that targeting these overexpressed coactivators like NCOA1 and NCOA3 is indeed a feasible approach to control breast cancer growth and/or metastasis." (PMID 26287601, 2015). "Recently, gossypol and bufalin have been identified as specific small molecular inhibitors for both NCOA1 and NCOA3 and have been shown to inhibit breast cancer cell growth and/or metastasis in culture and/or mice." (PMID 26287601, 2015). "Noteworthy, NCOA3 overexpression in breast cancer correlates with larger tumor size, higher tumor grade, as well as with the expression of ERBB2." (PMID 24304549, 2013). "Based on these observations NCOA3 has been under investigation as a target for treatment of breast cancer." (PMID 24304549, 2013). "Applying quantitative real-time RT-PCR (qRT-PCR), Western Blot analysis and chromatin immunoprecipitation, we analyzed the involvement of NCOA1, NCOA2, NCOA3 in the ERα-mediated transactivation of PLAC1 in the breast cancer cell lines MCF-7 and SK-BR-3." (PMID 24304549, 2013).
breast carcinoma (continued). "To consolidate our data in vivo, we analyzed expression of PLAC1 and NCOA3 transcripts in 48 human primary breast cancer tissue samples." (PMID 24304549, 2013). "In this study, we identified NCOA3 as a selective co-activator of ERα-mediated transactivation of PLAC1 in MCF-7 breast cancer cells." (PMID 24304549, 2013). "Gene amplification and overexpression of NCOA1, NCOA2 and NCOA3 in breast cancer has been described previously by several groups thus contributing to the development of cancer." (PMID 24304549, 2013). "Our data introduce PLAC1 as novel target gene of NCOA3 in breast cancer, supporting the important role of both factors in breast cancer biology." (PMID 24304549, 2013). "This is supported by studies showing that NCOA3 can stimulate the growth of breast cancer cell lines through estrogen-independent and estrogen-dependent mechanisms." (PMID 24304549, 2013). "In our study, we did not observe significant association between polymorphisms in NCOA3 and CCND1 with breast cancer risk." (PMID 21269472, 2011). "Burwinkel and colleagues reported a significant association of coding variants Q586 H and T960T of NCOA3 with familial breast cancer risk, and further suggested that familial breast cancer patients may condense the rare allele's contribution to the protective effect of breast cancer." (PMID 21269472, 2011). "We also identified three known poly-glutamine repeat polymorphisms, one in exon 20 of NCOA3., one in exon 15 of NCOR2., and one in exon 4 of SMARCA2; associations with these repeat polymorphisms and breast cancer risk will be examined in future studies." (PMID 19183483, 2009). "Moreover, research has shown that BET inhibitors (JQ1 and I-BET151) exert anti-cancer effects in breast cancer by inducing ferroptosis, with NCOA3, as a coactivator, interacting with NR5A2 to counteract BETi-induced ferroptosis." (PMID 39867656, 2024). "We next investigated whether breast cancer cells treated with NCOA3 inhibitors would exhibit any anti-proliferative/anti-survival effects." (PMID 36853387, 2023). "This shows that these three NCOA3, miR-17, and miR-20b may function as active biological markers and therapeutic targets in breast cancer resistance to taxol." (PMID 35265667, 2022). "Overexpression of NCOA3 promotes breast cancer chemoresistance to tamoxifen and paclitaxel." (PMID 32212785, 2020). "Moreover, NCOA3 is a selective co-activator of ERα-mediated transactivation of PLAC1, novel cancer-associated placental in MCF-7 breast cancer cells." (PMID 32212785, 2020). "However, recent studies have also implicated SR co-activators, such as AIB1 (amplified in breast cancer 1; also known as SRC-3 or NCOA3), as mediators of stem/progenitor cell formation." (PMID 30652114, 2018). "Furthermore, patients with breast cancer with high NCOA3 expression have a poorer prognosis than patients with low NCOA3 expression." (PMID 29854877, 2018). "In addition to finding previously well-known drivers, the identified modules pointed to other novel findings such as the interaction between NCOR2 and NCOA3 in breast cancer." (PMID 29023534, 2017). "Among these genes, NCOA3 (also known as AIB1 or SRC3) is an important oncogene in breast cancer." (PMID 28650955, 2017). "In the breast cancer core network, we found Fibronectin 1 (FN1), which is related to migration; FLT4 involved in angiogenesis; GSK3B, an anti-proliferative enzyme; KPNA2, a nucleopore transporter and the EP300-associated transcriptional activator NCOA3." (PMID 28775339, 2017). "Finally, both miR-17 and miR-20b levels were found to be significantly negatively correlated with NCOA3 mRNA levels in breast cancer tissues." (PMID 27831559, 2016). "Moreover, we demonstrated that miR-17 and miR-20b enhanced breast cancer cell sensitivity to taxol by directly targeting NCOA3." (PMID 27831559, 2016).